LPCAT3 (lysophosphatidylcholine acyltransferase 3)
Diseases named in the same sentence as LPCAT3 in open-access papers (continued):
Sharing a sentence is not in itself a finding about the gene and the disease.
tumor (24 papers, 2015 to 2026). "Knockdown of LPCAT3 not only inhibited ferroptosis but also contributed to the production of lipid-rich tumor-associated macrophages (TMEs), which impede host anticancer immunity and maintain the survival of cancer cells." (PMID 36457488, 2022). "IFN‐γ combined with mefloquine‐treated lung cancer cells and melanoma significantly reinforces tumour ferroptosis by activating LPCAT3 expression and sensitising tumour cells to PD‐1 blockade." (PMID 40045458, 2025). "On the other hand, by siRNA screening, we observed that knocking down any of these genes did not change the sensitivity of TRCs to RSL3, whereas knocking down of ACSL4 or LPCAT3 significantly decreased the sensitivity of cells to RSL3 in bulk tumor cells." (PMID 38720107, 2024). "More importantly, LXR-mediated induction of macrophage LPCAT3 can be used to reawaken the anti-tumour response." (PMID 35711841, 2022). "Given that the protein levels of ACSL4 and LPCAT3 were similar between TRCs and bulk tumor cells, we tested whether there were differences in the enzymatic activity." (PMID 38720107, 2024). "Similarly, disruption of LPCAT3-dependent phospholipid noticeably augments tumor formation in Apcmin mice." (PMID 36295848, 2022). "LPCAT3 is reported to regulate intestinal stem cell proliferation and enhance tumor formation." (PMID 34784264, 2022). "The ACSL4/LPCAT3/15-LOX axis not only oxidize AA or AdA to LPO to elicit ferroptosis but also may produce “find me” signals from ferroptotic tumor cells, mediating antitumor immunity." (PMID 32606298, 2020). "Further mechanistic investigations reveal that KLF1 inhibits ACSL4 expression via transcriptional repression and suppresses ferroptosis through the ACSL4/LPCAT3 axis, ultimately promoting HCC tumour growth as well as its advancement." (PMID 41656392, 2026). "LPCAT3 knockout reduced the composition of PUFA-PL in tumor cells, thereby inhibiting ferroptosis and promoting tumor progression." (PMID 37064872, 2023). "Notably, several studies have shown that LPCAT3 could affect the tumor microenvironment (TME)." (PMID 36457488, 2022). "LPCAT3 overexpression decreased the PC/PE ratio and unsaturated PC abundance on ER membranes in YUMM1.7 tumor cell-derived conditioned medium (CM) treated bone marrow (BM)-derived macrophages (BMDM)." (PMID 35711841, 2022). "Alternatively, inhibition of Lpcat3 or overexpression of master regulator of mevalonate pathway, SREBP2, markedly promotes intestinal tumor formation in tumor suppressor gene adenomatous polyposis coli (Apc) multiple intestinal neoplasia (Min), or Apc min-induced tumor mice." (PMID 32486083, 2020). "By using specific inhibitors toward LPCAT3 ((R)-HTS-3) or ACSL4 (rosiglitazone) in enzymatic activity assays, we found that the substrate conversion rate of LPCAT3 did not exhibit differences between TRCs and bulk tumor cells, whereas ACSL4 catalytic activity was significantly decreased in TRCs." (PMID 38720107, 2024). "Although the activation of LPCAT3 can inhibit tumor progression, there are currently no antitumor drugs that target LPCAT3, and further research is needed to determine the mechanism of action by which LPCAT3 promotes antitumor immunity and develop LPCAT3-targeted therapies." (PMID 37064872, 2023).
tumor (continued). "Notably, Lysophosphatidylcholine Acyltransferase 3 (LPCAT3) and LOX are respectively involved in the incorporation of arachidonic acid into membrane phospholipids and the oxidation of these phospholipids, collectively promoting ACSL4-dependent tumor ferroptosis induced by IFN-γ and arachidonic acid." (PMID 41035634, 2025).
cancer (17 papers, 2015 to 2025). A tumor composed of atypical neoplastic, often pleomorphic cells that invade other tissues. "Scd, Scd2, Dgat2, Fads2, Lpin1, Gpat3, Acaa2, Lpcat3, Pcyt2 and Pla2g4a have been reported to be closely associated with cancer." (PMID 35122680, 2022). "Higher LPCAT3 expression in acute myeloid leukemia, low-grade glioma, ovarian cancer, and uveal melanoma is associated with a poorer prognosis in patients with these cancers." (PMID 38893234, 2024). "Three genes (FMNL3, LPCAT3, and MUC1) were significantly differentially expressed between primary tumors and metastases in TCGA pan-cancer and were associated with overall, disease-specific, and/or progression-free survival." (PMID 40162116, 2025). "Meanwhile, its role in ferroptosis in addition to that of a marker, the mechanism by which LPCAT3 exerts specific anti-cancer effects needs to be further investigated." (PMID 35711841, 2022). "Studies in colon cancer models also suggest that LPCAT3 may inhibit the formation of this cancer." (PMID 38893234, 2024). "Lysophosphatidylcholine acyltransferase 3 (LPCAT3) promotes the induction of ferroptosis, while lysophosphatidylcholine acyltransferase 1 (LPCAT1) triggers ferroptosis evasion in cancer cells." (PMID 39624080, 2024). "Seven genes had lower expression in HBV+ live cancer compared with NAT samples, with LPCAT3 and MMP1 being the exceptions (P < 0.05)." (PMID 37004044, 2023). "Based on function, the 12 FRGs can be grouped into four classes: Lipid metabolism (GPX4, LPCAT3, ACSL5, and ACSL6), antioxidant metabolism (CD44, SESN2, and AIFM2), iron metabolism (CISD1 and HSPB1), and cancer metabolism (SOCS1, FH, and G3BP1)." (PMID 34784264, 2022). "The 12 FRGs are divided into 4 categories according to their functions: lipid metabolism (GPX4, LPCAT3, ACSL5, ACSL6), antioxidant (CD44, SESN2, AIFM2), iron metabolism (CISD1, HSPB1), and cancer metabolism (SOCS1, FH, G3BP1)." (PMID 35559049, 2022). "This has been attributed to the ability of these cancer cells to increase the synthesis and uptake of polyunsaturated fatty acids (PUFAs) and their resultant transformation into cytotoxic lipid peroxides (and lipid radicals) by the ACSL4/LPCAT3/ALOX pathway." (PMID 34429409, 2021).
metabolic disorders (5 papers, 2015 to 2025). "We conclude that alterations in AA metabolism along with myeloid Lpcat3 deficiency may secondarily affect AA homeostasis in the whole liver, leading to metabolic disorders and triglyceride accumulation." (PMID 33518513, 2021). "Therefore, an improved understanding of the mechanisms by which Lpcat3 and arachidonoyl PCs regulate lipid homeostasis could lead to new approaches to metabolic diseases." (PMID 25806685, 2015).
cardiac disease (2 papers, 2022 to 2023). "Overexpression of the lncRNA Ftx in cardiomyocyte shows to downregulates the ferroptosis pathway-related proteins (GSS and LPCAT3), indicating that the overexpression of lncRNA Ftx may play a protective role in cardiac disease by inhibiting ferroptosis in the cardiomyocyte." (PMID 36604692, 2023).
infection (2 papers, 2019 to 2022). The state of being infected such as from the introduction of a foreign agent such as serum, vaccine, antigenic substance or organism. "For ferroptosis, the significantly up-regulated proteins shared by the L. monocytogenes 10403s and M7 infection groups were Acsl5, Tf, Acsl1, Tfrc, and Lpcat3, and the significantly down-regulated proteins were Fth1 and Ftl1: neither changed significantly in the comparison group." (PMID 35682909, 2022).
LPCAT3 also shares sentences with these, for which no sentence is quoted: cardiovascular disease (2 papers); cervical cancer (2); chronic myeloid leukemia (2); colorectal cancer (2); glioma (2); acute leukemia (1); age-related macular degeneration (1); breast carcinoma (1); breast tumors (1); carotid atherosclerosis (1); cerebral infarction (1); coronary disease (1); endothelial dysfunction (1); gout (1); hyperlipidemia (1); hypertriglyceridemia (1); IgA nephropathy (1); kidney cancer (1); lipid metabolism disorders (1); liver cancer (1); lymphoma (1); melanoma (1); membranoproliferative glomerulonephritis type II (1); Non-Alcoholic Fatty Liver Disease (1); non‐alcoholic steatohepatitis (1); osteosarcoma (1); pancreatitis (1); retinopathy (1); Skeletal myopathy (1); systemic vasculitis (1).
A further 1 disease shares a sentence with LPCAT3 in 1 paper.